WEE1 (WEE1 G2 checkpoint kinase)
Diseases named in the same sentence as WEE1 in open-access papers (continued):
Sharing a sentence is not in itself a finding about the gene and the disease.
cancer (continued). "Furthermore, loss of the G1 checkpoint is frequent in tumors and potentially provides increased reliance on the G2 checkpoint, thereby selectively sensitizing cancer cells to checkpoint inhibitors like adavosertib (AZD1775), which is a highly selective inhibitor of WEE1." (PMID 39273409, 2024). "For this purpose, an inhibitor of the protein kinase WEE1 can be used (normally it stops the division of cells with damaged DNA), which enhances the expression of endogenous retroviruses (ERVs), the double-stranded transcripts of which stimulate the interferon response to cancer." (PMID 39351441, 2024). "The accumulation of p21/p27/WEE1 as three substrates of CRL induces the G2 cell cycle arrest against cancer cells with the treatment of MLN4924, and the co-treatment of MLN4924 with radiation enhances the induction of G2 cell cycle by the increased accumulation of p21/p27/WEE1." (PMID 37525282, 2023). "These cancer cells are expected to exhibit a vulnerability while they handle high levels of DNA replication stress, and exacerbating this replication stress using ATR inhibitors, or other checkpoint inhibitors that target CHK1 or WEE1, is thought to be a promising strategy for cancer therapy." (PMID 36892674, 2023). "In this light, Wee1 can be considered as a non-oncogene to which cancer cells are addicted." (PMID 33498235, 2021). "Notably, along with our study, we found that expression of p-RPS6, E2F1, FOXM1, and WEE1 protein was elevated significantly in de-differentiated LPS cancer cells, relative to nonmalignant ASC52telo cells." (PMID 33564073, 2021). "Combinations of DDA with DDRi targeting the replication-stress response (ATR, CHK1 and WEE1) could re-sensitise SLFN11-absent/low cancer models to the DDA treatment and were effective in upper gastrointestinal and genitourinary malignancies." (PMID 33339894, 2021). "The first small molecule to be reported bearing the pyridopyrimidine core was PD0166285 Although it showed a potent Wee1 inhibition activity (IC50 = 24 nM) in various cancer cell lines and xenografts, its clinical application is limited because of its non-selective Wee1 inhibition." (PMID 34639030, 2021). "Thus, the beneficial effects in cancer patients of AZD1775 can be mechanistically interpreted as due to interference with the function of Wee1 rather than of Plk1." (PMID 31200459, 2019). "The anticancer effects of this Wee1 inhibitor might be related to the genomic instability of the cancer cells, which results in sub-lethal DNA damage, rather than the G2 checkpoint kinase activity." (PMID 28978051, 2017). "Hence, it is possible that cancer cells with inherent reduced expression of ATR, Chk1, or Wee1 may respond to low concentrations of checkpoint kinase inhibitors, whereby normal cells could be spared." (PMID 25774168, 2015). "Although extensive further work is needed to draw a definitive link, it is tempting to speculate that this disruption might affect the expression of downstream clock-controlled genes regulating the cell cycle (such as Cyclin D1 and Wee1), contributing to tumorigenesis in HPV-related cancers." (PMID 24728990, 2014). "However, there are 29 clinical trials with the WEE1 inhibitor MK1775 (also known as AZD1775), which test its ability to impair alone or in combination with other cytostatic drugs (e.g., cisplatin, paclitaxel, 5-fluorouracil, and topotecan) the growth of different kinds of cancer." (PMID 29168755, 2017). "Therefore, both WEE1 and PKMYT1 may be useful targets for anti-cancer therapy." (PMID 29168755, 2017).
cancer (continued). "WEE1/PKMYT1 kinases are involved in different biological processes and they seem to play diverse roles in nonmalignant and in cancer cells." (PMID 32958072, 2020). "This review recapitulates and discusses the most recent findings on the biological function of WEE1/PKMYT1 during the cell cycle and in the DNA damage repair, with a focus on their dual role as tumor suppressors in nonmalignant cells and pseudo-oncogenes in cancer cells." (PMID 32958072, 2020). "Moreover, DNA damage proteins and cancer cells have specific properties, including cancer-specific DDR defects and lack of G1 checkpoint control, that may highlight particular vulnerabilities of the cancer, supporting PARP, ATR, ATM, CHK1/2, and WEE1 as therapeutic targets." (PMID 34930377, 2021).
tumor (632 papers, 1988 to 2026). "Despite a lack of in vivo efficacy of the chosen drug combination, genetic WEE1 KD in an in vivo PDX model led to reduction of tumor growth, as well as increased survival of immune-deficient mice, proving WEE1 as a promising target in LFS-associated SHH-MB." (PMID 41585496, 2026). "Studies indicate that inhibiting WEE1 causes tumor cells to prematurely enter mitosis with unrepaired DNA, leading to cell death." (PMID 40949156, 2025). "Upregulation of Wee1 has been found in several tumours, and it is frequently associated to a poor prognosis." (PMID 39528354, 2025). "Preclinical studies have shown that WEE1 inhibitors, either as monotherapies or in combination with targeted agents, are effective across various tumor types harboring KRAS mutation." (PMID 40885709, 2025). "Our data demonstrated that high Wee1 expression levels sensitized MUC‐1 to AZD1775 anti‐tumour effects, causing a further reduction in cell proliferation and increase in apoptotic cells." (PMID 39528354, 2025). "TUNEL staining showed a significant increase in the number of positive cells in the tumors of the treatment group, suggesting that the WEE1 inhibitor caused apoptosis of the tumor cells." (PMID 39335109, 2024). "We also noted a SETD2 (p.S1885N) mutation that was present only in the recurrent tumor which was identified as a predicted biomarker of response to WEE1 inhibition." (PMID 39935847, 2024). "As H3K36me3 loss is linked to more aggressive tumours and worse prognosis, it is important to include such patients that would benefit from WEE1 inhibitor treatment." (PMID 37528416, 2023). "Together, pharmacological inhibitors targeting the components of the ATR/CHK1/WEE1 pathway in 3 tumor entities expressing most KRAS mutations have reached phase II clinical trials." (PMID 36313934, 2023). "From this perspective, the ATM/CHK2/WEE1 pathway inhibitors cause the increased expression of PD-L1 in tumor cells and promote immune escape, so they are more suitable for the combined application of PD-1/PD-L1 inhibitors." (PMID 37109350, 2023). "From a wide perspective, spontaneous inhibition of WEE1 and Chk1 takes over premature mitosis before DNA replication, causing apoptosis and disturbed tumor growth." (PMID 35477702, 2022). "The markedly enhanced efficacy was likely due to the enhanced antigen presentation as a result of higher tumor mutation load considering the function of WEE1 in DNA damage and repair." (PMID 35006413, 2020). "Conceptually, we therefore believe that understanding haspin contribution to the Wee1/Cdc25 pathway can shed light in long term on mechanisms underlying tumor development." (PMID 33585466, 2020). "Taken together, these data highlight the potential of targeting upstream growth factor signalling receptors, downstream signalling pathways such as PI3K/mTORC and G2/M associated checkpoint proteins such as WEE1 in palbociclib resistant tumours." (PMID 32307447, 2020).
tumor (continued). "We demonstrate that Wee1 up-regulation follows tumor progression and is associated with thicker tumors, ulceration and decreased relapse-free survival." (PMID 22719872, 2012). "Interestingly, the majority of the tumor cells were polyploid, suggesting that increased DNA damage due to loss of Wee1 during proliferation drives the endoreplication of these tumorigenic luminal cells." (PMID 38627401, 2024). "Thus, as part of a mechanism of adaptation to CCNE1-associated replication stress, WEE1 can enhance tumor cell survival." (PMID 35315355, 2022). "In HGGs, higher WEE1 expression levels were associated with higher tumor grades." (PMID 35158967, 2022). "Taken together, these data suggested that a loss of Wee1 expression may both promote tumor aggressiveness and be a useful prognostic indicator." (PMID 34639030, 2021). "We demonstrate here that the defects in tumor cell death described in association with very high levels of brachyury in tumor cells could be alleviated via the use of a WEE1 inhibitor, which is currently undergoing clinical testing." (PMID 29774202, 2018). "We also demonstrate here that the defects in tumor cell death described in association with very high levels of brachyury could be alleviated via the use of a WEE1 inhibitor." (PMID 29774202, 2018). "Altogether, these data strongly argue that the combined treatment of U2OS cells with Chk1 and Wee1 inhibitors synergistically increases replication catastrophe, and that this may be the major cause for the synergistic anti-tumor effects of these inhibitors." (PMID 28030798, 2017). "We certainly do not dispute the data from other laboratories 23, in fact, we hope that future studies may help determine which tumor systems that harbor BRCA/FA-homologous repair gene defects may cause resistance or sensitivity to WEE1 inhibition." (PMID 27616351, 2016). "Moreover, the loss of Wee1 kinase activity also appeared to be roughly equivalent in each of the tumor cell lines based on the levels of CDK Y15 phosphorylation." (PMID 24927813, 2014). "Our study shows that CHD5 is a NuRD-associated transcriptional repressor and identifies WEE1 as one of the CHD5-regulated genes that may link CHD5 to tumor suppression." (PMID 25247294, 2014). "We also noted that CDDP-treatment of pxn100 tumours induced the expression by >2.5-fold of genes encoding proteins that regulate the G2M cell cycle checkpoint (WEE1, CCNB1, CDC25C) and a gene encoding a protein involved in the anaphase promoting complex in mitosis (CDC6)." (PMID 15452549, 2004). "In immunocompetent mouse models, the combination not only delays tumor progression and improves survival beyond either monotherapy but also enhances lymphocytes infiltration and overcomes resistance associated with olaparib insensitivity and high WEE1 expression." (PMID 40949156, 2025).
tumor (continued). "Furthermore, induction of DNA damage marker γH2Ax Ser139 was observed in both premalignant cells and tumor cell lines after Adavosertib exposure, indicating that the loss of Wee1 activity impacts replication stress and associated DNA damage, or impairs DNA repair signaling." (PMID 32047167, 2020). "Finally, we demonstrate that WEE1 inhibitor AZD1775 regresses H3K36me3-deficient tumor xenografts." (PMID 26602815, 2015). "Preclinical studies have demonstrated synergistic anti‐tumour effects when ATR or WEE1 inhibitors are combined with ICIs." (PMID 41537447, 2026). "There was a significant difference in survival, as all five mice from the control group died due to tumor development during observation period, while two mice in the WEE1 KD group remained alive (p = 0.044)." (PMID 41585496, 2026). "WEE1 inhibition impairs DNA repair in dendritic cells, augments T‐cell priming and activation and cooperates with PD‐1/PD‐L1 blockade to strengthen anti‐tumour immunity." (PMID 41537447, 2026). "Clinical studies are required to test the combination of vincristine and a BBB-penetrant WEE1 inhibitor in LFS SHH-MB, as well as possibly in other LFS-associated tumor entities." (PMID 41585496, 2026). "WEE1, a key regulator of the G2/M checkpoint, in DDR‐defective tumours, WEE1 inhibition exacerbates genomic instability by releasing this brake." (PMID 41537447, 2026). "Research has shown that PARPis combined with a WEE1 inhibitor (WEE1i) target the replication stress response to enhance anti‐tumour activity and overcome PARPi resistance." (PMID 41537447, 2026). "Upregulation of G2/M Wee1 kinase was shown in FLNA‐deficient mouse neural progenitor cells, and it has been reported in several tumours." (PMID 39528354, 2025). "Transfection of MUC‐1 with siRNA targeting Wee1 resulted in a strong reduction in cell proliferation and an increase in apoptosis, consistent with the finding that dysregulated Wee1 function has a role in tumour progression." (PMID 39528354, 2025). "Protein expression analyses in tumour and normal adrenal samples revealed elevated Wee1 and reduced FLNA levels in ACC compared to normal adrenal tissues." (PMID 41226387, 2025). "Inhibition of WEE1 under these conditions induces synthetic lethality, as tumour cells lose the ability to repair DNA damage, prematurely enter mitosis, and ultimately undergo cell death." (PMID 40859871, 2025). "In the leptomeningeal carcinomatosis mouse model, the combined inhibition of EGFR and WEE1 significantly suppressed tumor growth." (PMID 40518016, 2025). "WEE1 was primarily localized in the nuclei of tumor cells and was more abundant in the tumor from patient#3 than in the other patients." (PMID 40551232, 2025). "In an orthotopic breast cancer model, co-targeting ATR and Wee1 led to tumor-selective synthetic lethality, with tumor remission and metastasis impairment." (PMID 40422251, 2025). "In melanoma, miR-195 was identified as a tumour-promoting miRNA that promotes tumour growth, invasion, and migration by inhibiting WEE1 protein cellular expression, blocking cell cycle arrest, and enhancing uncontrolled cellular proliferation." (PMID 39736850, 2025). "One study has shown that WEE1 deletion in mammary epithelial cells of mice leads to increased tumor growth and concluded that WEE1 functions as a tumor suppressor." (PMID 40565165, 2025). "Recent studies have found that ATRX alterations contribute to immune escape and increased tumor growth in pleomorphic sarcoma and that ATRX-deficient tumor cells were particularly susceptible to the WEE1 inhibitor AZD1775." (PMID 40563612, 2025). "Compared to PDXO#1 and #2 and PDX#1 and #2, PDXO#3 and PDX#3 with substantially high WEE1 expression had the greatest cytotoxicity and tumor growth suppression in response to AZD1775 therapy." (PMID 40551232, 2025).